INS (insulin)
Diseases named in the same sentence as INS in open-access papers (continued):
Sharing a sentence is not in itself a finding about the gene and the disease.
autoimmune disease (continued). "T1D is considered an autoimmune disease that affects individuals from a young age and requires insulin-dependent treatment due to defects in insulin secretion in the individual." (PMID 32711560, 2020). "T1DM is an autoimmune disease characterized by the destruction of insulin-producing beta cells in the pancreas and the absolute insufficiency of insulin secretion." (PMID 30909474, 2019). "DM1 is an autoimmune disease characterized by an absolute deficit of insulin due to selective destruction of PBC mediated by lymphocytes T and autoantibodies." (PMID 29670917, 2018). "As an important independent regulatory molecule, microRNA-15a is involved in the regulation of cell apoptosis and proliferation, autoimmunity disease, cardiovascular disease and insulin synthesis." (PMID 28877683, 2017). "T1D is an autoimmune disease of the pancreatic islet in which insulin-producing beta cells are destroyed by auto-reactive T-cells and monocytic cells." (PMID 28149833, 2017). "T1D is an unpreventable, autoimmune disease of the islet of Langerhans by which insulin-producing beta cells are destroyed by auto-reactive T-cells and monocytic cells." (PMID 28149833, 2017). "Type 1 diabetes (T1D) is a CD4+ T cell-driven autoimmune disease resulting from the destruction of insulin-producing pancreatic beta cells." (PMID 27656680, 2016). "T1D is a T cell mediated autoimmune disorder which targets and destroys insulin producing pancreatic β cells." (PMID 26843788, 2015). "Type 1 diabetes (T1D) is an autoimmune disease which is characterized by progressive destruction of insulin producing pancreatic islet β cells." (PMID 26843788, 2015). "T1D is a multifactorial autoimmune disease in which insulin producing β cells, which reside in the islets of Langerhans in the pancreas, are attacked and killed predominantly by autoreactive T lymphocytes." (PMID 24478773, 2014). "T1D is one of the most common autoimmune disorders, characterized by a T cell-mediated destruction of insulin-producing beta cells in the pancreas." (PMID 25226393, 2014). "Type 1 diabetes (T1D) is considered as a debilitating autoimmune disease that results from T cell-mediated destruction of insulin-producing beta cells." (PMID 24410812, 2014). "Type-1 diabetes (T1D) is an autoimmune disease in which insulin-secreting pancreatic beta cells are destroyed by the immune system." (PMID 24759943, 2014). "Type 1 diabetes (T1D) is a T cell–mediated autoimmune disease characterized by the destruction of insulin-secreting pancreatic β cells." (PMID 23323860, 2013). "Type 1 diabetes (T1D) is a polygenic autoimmune disease characterized by the destruction of insulin-secreting pancreatic β cells." (PMID 23323860, 2013). "In particular, cases of type 2 DM (T2DM) have been increasing in contrast to cases of type 1 DM (T1DM), an autoimmune disease resulting in the destruction of insulin-producing beta cells of the pancreas and the failure to produce insulin." (PMID 20181067, 2010). "Type 1 (insulin-dependent or juvenile-onset) diabetes mellitus (T1D) is an autoimmune disease resulting in the destruction of the insulin-producing pancreatic β-cells and requiring continuous glucose monitoring and insulin treatment." (PMID 19371422, 2009). "T1D is an autoimmune disease that results in destruction of insulin-producing beta cells of the pancreas." (PMID 20041220, 2009). "T1D is an autoimmune disease resulting in the inability to produce insulin and metabolize glucose, necessitating self‐management through counting carbohydrates and proportionate administration of insulin through multiple daily injections or constant subcutaneous insulin infusion (“insulin pump”)." (PMID 40958557, 2025). "In the context of T1D, an autoimmune disease characterized by T-cell-mediated destruction of insulin-producing β-cells, potassium dysregulation could influence immune responses or β-cell vulnerability, potentially contributing to disease risk." (PMID 41156550, 2025).
autoimmune disease (continued). "Future research should aim to identify epigenetic markers that predict individual immune responses to different diets and investigate how modulating gut microbiota through personalized nutrition can reduce inflammation, improve insulin sensitivity, and prevent autoimmune diseases." (PMID 40443829, 2025). "Last but not least, considering the lack of specific INSR inhibitor and the colitis-exacerbating effect of co-inhibitors, the development of insulin-specific inhibitors is urgently needed to study the INSR-targeted therapy for patients with IBD or other autoimmunity disease." (PMID 38243324, 2024). "While type 1 diabetes (T1D) is caused by an autoimmune disease that results in the absence of insulin secretion, type 2 diabetes (T2D) is caused by both the resistance and inadequate secretory response of insulin." (PMID 39000600, 2024). "DM can be classified broadly into two types: type 1 (T1DM), which is an autoimmune disease characterized by complete deficiency of insulin secretion, and type 2 (T2DM), which accounts for 90% of DM cases worldwide, is due to insufficient insulin secretory response and resistance to insulin action." (PMID 36766861, 2023). "Clinical data such as age, BMI, metabolic control, insulin use, personal history of autoimmune diseases or family history of T1D may serve as elements of suspicion, but none of them is fully discriminative." (PMID 37138364, 2023). "Whereas, adequate replacement of VD not only improves the blood glucose level via controlling the insulin signaling but also protects against cardiovascular diseases, autoimmune diseases, infectious diseases, and musculoskeletal disorders by regulating lipogenesis and inflammation." (PMID 37881399, 2023). "Several human leukocyte antigen (HLA) gene polymorphisms of MHC class I and II, insulin gene short VNTR (variable number tandem repeat), and a nonsynonymous CNR2 SNP (Q63R) are risk alleles that co-segregate with several autoimmune diseases." (PMID 35115945, 2021). "With the exception of T1D, where autoantigens are generated against highly expressed proteins of the insulin-producing beta cells of the pancreas, the relationships between autoantigenic proteins and target tissues in the other autoimmune disease examples remains poorly understood." (PMID 33763057, 2021). "T1DM is an autoimmune disorder characterised by an almost complete defect in insulin secretion." (PMID 32244496, 2020). "An anti-inflammatory function of IL-27 has been reported in several autoimmune diseases; however, in type 1 diabetes (T1D), an autoimmune disease where autoreactive cytotoxic T cells attack insulin-producing beta cells, IL-27 has been shown to have a dual role and contradictory effects." (PMID 31949260, 2020). "Based on the information available in the literature, a broad panel of antibodies should be used for rheumatologic and autoimmune diseases, and the search for anti-insulin antibodies should always be included, as these correlated with remission in this series of cases." (PMID 32813762, 2020). "Type 1diabetes (T1D) is an autoimmune disease in which insulin-producing beta cells in the pancreas are destroyed by the human body pathologically, preventing the body from being able to produce enough insulin to adequately regulate blood glucose levels." (PMID 32312302, 2020). "T1D is an autoimmune disease in which beta cells that produce insulin are destroyed." (PMID 32711560, 2020). "Moreover, DM results from the selective destruction of insulin-producing β-cells in the pancreatic islets and is primarily a T cell-mediated autoimmune disease directed against one or more β-cell autoantigens." (PMID 31443712, 2019). "In addition, one other microRNA, MIR15A, is also known to be an important independent regulatory molecule involved in the control of cell proliferation and apoptosis, cardiovascular and autoimmune diseases, and the synthesis of insulin." (PMID 29755503, 2018).
autoimmune disease (continued). "In patients with family history of DM, the OGTT could help to detect the insulin secretion impairment even more if those patients have other autoimmune disease." (PMID 30346951, 2018). "Patients with reproductive failure, 1st and/or 2nd degree relatives with metabolic or autoimmune disorders, normal BMI, low insulin levels after OGTT could benefit from additional immune testing to rule out pancreatic autoimmunity." (PMID 30346951, 2018). "It should be noted that as well as statistical effects, concurrent medical conditions, such as infections or autoimmune disease, might be expected to boost insulin antibody titers in a few individuals as part of more general immunological activation." (PMID 29355435, 2018). "T1D is a complex, multifactorial autoimmune disease in which the insulin-producing pancreatic beta cells are destroyed, leaving the patient dependent on insulin injections for sustaining life, and in risk of premature death due to acute- and late complications." (PMID 26612984, 2016). "Whether T1D - an autoimmune disease affecting islet beta cells of the pancreas producing insulin - has a viral origin is still a debate." (PMID 21255393, 2011). "Additionally, insulin insensitivity may reflect a more aggressive form of autoimmune disease, via immunoinflammatory factors that mediate both β-cell destruction and insensitivity." (PMID 40004639, 2025). "Given that T1DM is characterized as an autoimmune disease, where immune cells attack and destroy pancreatic β -cells, it is crucial to consider the immunomodulatory properties of BMCs and their ability to differentiate into insulin-producing cells when utilizing BMT for T1DM treatment." (PMID 39014283, 2024). "High rate of insulin production may result in the formation of neo-autoantigens created via post-translational modification of islet proteins, which attract immune cells and drive an autoimmune disease process." (PMID 37919779, 2023). "Thus, CBLB is a key gene of T1DM, and downregulated CBLB participating in the insulin signaling pathway may contribute to the autoimmune disease of T1DM." (PMID 34006268, 2021). "Indeed, the known T1D susceptibility loci follow this observation: while both CTLA4 and PTPN22 loci are associated with several autoimmune diseases, the insulin VNTR locus is likely to be T1D-specific rather than a general autoimmune locus." (PMID 16519819, 2006). "Interestingly, different risk scores may include different polymorphisms within the same gene (e.g., INS, IL2RA, and BACH2 contain distinct polymorphisms in the Sharp and Bonifacio scales), highlighting their overall significance in the development of autoimmune disorders." (PMID 41153727, 2025). "Medical complications of the two autoimmune disorders in children and adolescents have been evaluated, particularly in those treated with glucocorticosteroids (GCS) and insulin." (PMID 34999914, 2022). "Human type 1 diabetes (T1D) is considered to be an autoimmune disease, with CD8+ T-cell-mediated cytotoxicity being directed against the insulin-producing beta cells, leading to a gradual decrease in beta cell mass and the development of chronic hyperglycemia." (PMID 25005747, 2014). "The case highlights the importance of considering LADA in patients with poor glycemic control despite standard T2DM therapy, especially when autoimmune diseases are present: positive anti-GAD antibodies, low C-peptide, and improved outcomes with insulin support the diagnosis." (PMID 41024896, 2025). "T1DM is an autoimmune disease in which the immune system destroys pancreatic insulin‐producing cells, leading to minimal or no insulin production." (PMID 40290901, 2025). "In contrast, autoimmune diseases that arise later or target non‐β‐cell antigens do not benefit from this coordinated enhancement of insulin‐specific central and regulatory tolerance." (PMID 40968543, 2025).
autoimmune disease (continued). "As a relatively common autoimmune disease, T1D is charactered by a complete lack of insulin due to the destruction of pancreatic beta cells, and insulin therapy must be given." (PMID 38585265, 2024). "The protective effect of hydroxychloroquine on blood glucose metabolism is not only observed in autoimmune diseases but also in individuals without systemic inflammation but taking hydroxychloroquine to improve insulin sensitivity." (PMID 39568816, 2024). "T1DM is an autoimmune disease in which the insulin-producing pancreatic β-cells are damaged resulting in the lack of insulin production." (PMID 37755075, 2023). "Antibody reactivity to insulin was first described in individuals undergoing exogenous insulin administration but people with different autoimmune diseases can also produce IAA in the absence of prior treatment with the hormone." (PMID 36759347, 2023). "Type 1 DM is an autoimmune disease resulting from an immune system attack on the islet β cells that produce insulin, leading to an inflammatory process and a lack of insulin in the body." (PMID 36364880, 2022). "This autoimmune disease is the result of a combination of genetic and environmental factors that intervene as triggers of an autoimmune reaction that selectively destroys PBC, resulting in an absolute insulin deficit." (PMID 29670917, 2018). "T1D, like other autoimmune diseases, is a composite of genetic and non-genetic effects, leading to the destruction of insulin-secreting cells." (PMID 28829396, 2017). "The disease, as with other autoimmune diseases, is due to the interaction of genetic and non-genetic effects, which induce a destructive process damaging insulin-secreting cells." (PMID 28829396, 2017). "Type-1 diabetes (T1D) is an autoimmune disease targeting insulin-producing beta cells, resulting in a lack of insulin production that requires lifelong exogenous insulin administration." (PMID 24205242, 2013). "TNF-α, a key cytokine, plays a significant role in autoimmune diseases, with TNF-α inhibitors revolutionizing their treatment; they achieve this by impairing insulin signalling by increasing the serine phosphorylation of insulin receptor substrates, leading to decreased insulin sensitivity." (PMID 40407536, 2025). "In this autoimmune disease, very little or no insulin is produced by the pancreas." (PMID 33628471, 2021). "In the context of autoimmune disease, the outcomes of this immunization include not only formation of insulin and GAD autoantibodies in B-cells but also, as demonstrated in the present study, the latent pre-activation of T-lymphocytes by insulin as an autoantigen in T-cells, as well as by GAD." (PMID 28986401, 2017). "However, the titers of these autoantibodies were higher in HT patients, but there was no significant relation to insulin secretion and glucose tolerance at that moment and stage of autoimmune diseases." (PMID 28724056, 2017). "Recent studies have reported that PPARγ plays an important immunoregulatory function in autoimmune diseases, such as experimental autoimmune encephalomyelitis (EAE), allergic airway inflammation, trinitrobenzene sulfonic acid-induced colitis, and insulin resistance." (PMID 25383620, 2014). "Our data do not argue against the notion of PCOS being an autoimmune disease in at least some patients, as there are many more relevant antigen candidates potentially affecting the gonadal axis and androgen concentrations, or the metabolic axes, body composition and insulin sensitivity." (PMID 33798258, 2021).
COVID-19 (389 papers, 2020 to 2026). A disease caused by infection with severe acute respiratory syndrome coronavirus 2. "On the other side, insulin and sulfonylureas appears to be risk factors for COVID-19 hospitalization and infection." (PMID 39942512, 2025). "Direct infection of adipose tissue by SARS-CoV-2 has emerged as a potential mechanism underlying adipose tissue dysfunction and insulin resistance in COVID-19." (PMID 40564201, 2025). "A retrospective study of 3,305 cases from Wuhan, China, indicated that insulin treatment for patients with COVID-19 comorbid with T2DM was associated with a significant increase in mortality (27.2% versus 3.5%)." (PMID 40469441, 2025). "Insulin was associated with a higher risk of all-cause mortality in patients with COVID-19 with T2DM, while metformin and AGIs were associated with a lower risk." (PMID 38755442, 2024). "We have previously observed that increasing severity of respiratory failure in patients with severe COVID-19 is associated with increased insulin demand." (PMID 39532941, 2024). "The cytokine storm caused by COVID-19 is not only localised to the lungs, but it causes widespread systemic inflammation, which damages different organs, including the insulin-producing organ, the pancreas." (PMID 38651404, 2024). "In fact, hyperglycemic individuals treated with insulin showed lower risk to develop severe COVID-19." (PMID 38378550, 2024). "SGLT-2 inhibitors therapy was a protective factor against SARS-CoV-2 infection and against COVID-19 hospitalization while sulfonylurea and insulin therapies were COVID-19 hospitalization risk factors." (PMID 38538694, 2024). "The underlying mechanism for insulin’s association with COVID-19 hospitalization and death outcomes is unclear." (PMID 38536830, 2024). "SGLT-2 inhibitors therapy was a protective factor against SARS-CoV-2 infection and against COVID-19 hospitalization, sulfonylurea was the COVID-19 hospitalization risk factor, while insulin was a risk factor for all outcomes." (PMID 38538694, 2024). "In conclusion, we show that prone positioning is safe with respect to glycaemic control and demonstrate an intriguing association between prone ventilation and insulin demand in patients with AHRF due to COVID-19." (PMID 39532941, 2024). "As the scientific community continues to investigate the complexities of long COVID-19, ongoing research aims to unravel the precise mechanisms underlying the connection between the lingering effects of the virus and insulin resistance." (PMID 39338165, 2024). "Glucosuria in COVID-19 patients results from worsening glucose metabolism, as already indicated by diagnostic biomarkers, driven by inflammation, hypoxia, insulin resistance, and tubular dysfunction." (PMID 39728505, 2024). "Our study did find insulin and sulfonylurea to be risk factors for COVID-19 hospitalization, though." (PMID 38536830, 2024). "Differences according to COVID-19 RP were identified, low RP was associated with older age, male sex, lower psychiatric comorbidity, lower psychiatric treatment, and lower insulin therapy." (PMID 38349901, 2024). "Overall comorbidity burden was one of the strongest risk factors for severe COVID-19 and the risk was also increased in patients prescribed insulin, proton pump inhibitors, diuretics, antiplatelets or immunosuppressants." (PMID 38186903, 2024). "An additional study investigated the application of insulin in hyperglycemic COVID-19 patients, and insulin infusion led to a lower risk of severe disease compared to patients without insulin therapy." (PMID 37631970, 2023). "Other factors are also linked to blood glucose fluctuation, particularly in COVID-19 patients, including the use of glucocorticoids that can cause glycemic excursions; thus, their impact should be considered during insulin pattern setup." (PMID 37048638, 2023).